IL6 (interleukin 6)
Diseases named in the same sentence as IL6 in open-access papers (continued):
Sharing a sentence is not in itself a finding about the gene and the disease.
Obesity (continued). "Other studies have also demonstrated that the development of obesity increases the secretions of various pro-inflammatory chemokines and cytokines from adipose tissues, such as tumor necrosis factor-alpha (TNF-α), interleukin-1beta (IL-1β), IL-6 and monocyte chemoattractant protein-1 (MCP-1)." (PMID 32143330, 2020). "In addition, normal weight obesity patients had significantly higher levels of inflammatory cytokines and higher IL-6 concentrations than those in non-obese and obese patients." (PMID 32595758, 2020). "Notably, both IL-6 and CRP are elevated with obesity and modulate MDSC dynamics." (PMID 33123173, 2020). "One of the main factors contributing to the development of obesity is the consumption of a high-fat diet (HFD), characterized by high leptin levels in humans, mice and zebrafish (Danio rerio) and increase in tumor necrosis factor α (TNF-α) and interleukin 6 (IL-6) levels." (PMID 32635261, 2020). "However, obesity didn’t correlate with systemic IL-6 levels and neither did we find any correlation with IL-6 and other clinicopathological factors in our cohort." (PMID 32298379, 2020). "Data from animal and human studies have shown that obesity leads to a systemic proinflammatory state as indicated by higher plasma concentrations of various inflammatory markers, including CRP, interleukin 6 (IL-6), tumor necrosis factor α (TNF-α), and monocyte chemoattractant protein 1 (MCP-1)." (PMID 31192262, 2019). "Even both cytokines are secreted by adipose tissue and are involved in inflammation pathways, the salivary level of leptin was not correlated with the IL-6 level (r = 0.07, P = 0.41), six cases of obesity were characterized by elevated IL-6 and normal level of salivary leptin." (PMID 30605486, 2019). "In particular, we address the question as to whether circulating levels of pro-inflammatory markers, such as leptin and IL-6, or markers of cerebral plasticity, such as BDND and S100B, are related to the temporal sensitivity in obesity, through a cross-sectional study." (PMID 31664059, 2019). "Conversely, TNF-α was positively related, and IL-6, leptin, insulin, total n-6, n-3 and n-6/n-3 PUFAs in whey breastmilk were negatively correlated to several infant growth measures in offspring of women without overweight or obesity." (PMID 31141526, 2019). "In addition to IL-6, we found CCL-2 was increased drastically in obesity EAE mice." (PMID 31507583, 2019). "Additionally, the administration of vaspin led to significantly smaller adipocytes, reduced expression of IL-6, and increased expression of GLUT4, suggesting that vaspin could potentially be used to increase insulin sensitivity and inhibit obesity." (PMID 30909620, 2019). "In 209 patients with obesity a multiple regression model was computed with REE as the dependent variable and sex, waist, FFM, FM, homeostasis model assessment-insulin resistance (HOMA), interleukin-6 and High Density Lipoprotein-cholesterol as the independent variables." (PMID 31440209, 2019). "Interestingly, selectively blocking IL-6 trans-signaling, unlike complete ablation of IL-6 signaling, does not exacerbate obesity-induced weight gain or insulin resistance." (PMID 31191541, 2019). "The sour cherry extract significantly decreased the IL-6 levels, which was comparable to the results of other groups, but it is worth mentioning that there are reports where anthocyanin treatment did not prove to be effective in decreasing IL-6 levels in a diet induced obesity model." (PMID 31438590, 2019). "Dysregulated energy homeostasis including hyperphagia and exacerbated obesity was elicited prior to the presence of the amyloid pathology in the hypothalamus of HFD APP/PS1 transgenic mice; nevertheless, cortical neuroinflammation and the level of serum Aβ and IL-6 were significantly elevated." (PMID 30096853, 2018).
Obesity (continued). "A recent study found that obese patients have lower levels of proinflammatory cytokines (IL-6, IL-8) and surfactant protein D, The lack of reduced mortality related to obesity might be due to low grade inflammatory response." (PMID 29883469, 2018). "Also, it is reported that obesity‐induced increases in IL‐6 did not correlate with the incidence rate of acute kidney injury, while oxidative stress marker plasma F2‐isoprostanes was increased in those patients." (PMID 29632818, 2018). "However, considering that fat mass is a source of inflammatory cytokines, including IL-6 and TNF-alfa, it is to be expected that increasing the amount of fat mass (obesity) will contribute to the development of a chronic inflammatory state that can lead to inflammatory bone loss." (PMID 30400559, 2018). "However, how the low-grade nature of IL-6 in obesity impacts on CRC development and progression has not been investigated yet." (PMID 29695802, 2018). "Dendritic cells from the circulation of older individuals may also have the potential to guide pro-on within adipose tissue due to increased intracellular IL-6 and TNF-α and increased expression of co-stimulatory and activation markers, as is observed in the context of obesity." (PMID 29479350, 2018). "In addition, blood-brain barrier (BBB) permeability was increased in a model of obesity-induced by HFD and also aggravated cognitive deficit by increasing the exposure of the brain to various cytokines, including LPS, IL-1β, IL-6, and tumor necrosis factor alpha (TNFα)." (PMID 29316965, 2018). "According to previous studies, HFD intake and obesity induce glia activation and central neural inflammation, as demonstrated by an increase of the gliosis marker GFAP as well as pro-inflammatory mediators (NF-kB, IL-6 and IL-1β) and the infiltration of immune cells." (PMID 30134549, 2018). "Pro-inflammatory cytokines such as IL-1, IL-6, and TNF-α produced by adipose tissue or in response to stress can activate the hypothalamic-pituitary-adrenal (HPA) axis; hence the relationship among obesity, systemic inflammation, and stress reactivity is cyclical in nature." (PMID 30538987, 2018). "In obesity, inflammation can occur due to increased levels of chemokines (such as CCL2 and CXCL1) and inflammatory cytokines (such as tumor necrosis factor α (TNF-α) and interleukin-6 (IL-6)) secreted from accumulated fat in hepatocytes and adipocytes, causing insulin resistance." (PMID 29967759, 2018). "Recent studies have confirmed that obesity is a state of low-grade chronic inflammation that is characterised by increased concentrations of C-reactive protein (CRP), tumour necrosis factor-alpha (TNF-α), interleukin-6 (IL-6), and other inflammatory markers in the blood." (PMID 30914847, 2018). "Likewise diabetes, obesity generally constitutes a chronic inflammatory state, particularly elevated leukocyte counts, activity of granulocyte phagocytosis and oxidative burst, and increased levels of TNF-α and IL-6." (PMID 29104871, 2017). "Obesity leads to lipid accumulation and activates the c-Jun N-terminal kinase (JNK) and nuclear factor-kappa B (NF-κB) signaling pathways, which consequently increase production of pro-inflammatory cytokines, such as tumor necrosis factor-alpha (TNF-α) and interleukin-6 (IL-6)." (PMID 29037210, 2017). "The accumulation of excess lipids in fatty tissue in obesity leads to adipocyte dysfunction, hypoxia, oxidative stress, and chronic inflammation, accompanied by the release of proinflammatory and diabetogenic cytokines, such as tumor necrosis factor alpha (TNF-α), interleukin 6 (IL6), etc.." (PMID 29321950, 2017). "This is a very important pathway in obesity since increased circulating leptin levels lead to development of leptin resistance by chronic activation of JAK/STAT3 in the CNS, whereas in the peripheral organs chronic IL-6-induced JAK/STAT3 impairs insulin action." (PMID 29170528, 2017).
Obesity (continued). "The significant increase in serum levels as well as tissue content of IL-6 and sIL-6Rα observed from 8 to 16 weeks of HFD feeding in both IL-6RαT-KO and their control IL-6Rαf/f confers an upregulated IL-6 trans-signalling during prolonged progression of diet-induced obesity." (PMID 28466852, 2017). "Indeed one of our previous studies found that higher levels of circulating IL-6 and CRP in MDD patients may be explained, at least in part, by obesity." (PMID 28670290, 2017). "Mechanistically, the obesity-related inflammation includes mTOR, JAK, JNK, IKKβ, and PI3K/Akt signaling pathways involved in inflammation activation, which contribute to increased secretion of cytokines, such as TNF-α, IL-6, and resistin, and decreased secretion of adiponectin." (PMID 28182687, 2017). "It still remains unclear that whether elevations of inflammatory markers like tumor necrosis factoralpha (TNF-α), interleukin-6 (IL-6) and high sensitive C-reactive protein (hs-CRP) are related to PCOS or are a function of obesity, abdominal adiposity, or both." (PMID 28042411, 2017). "In contrast, in obesity, interferon (IFN)-gamma and lipopolysaccharide (LPS) drive the polarization of recruited monocytes toward inflammatory M1-type macrophages and produce a large amount of nitric oxide by expressing inducible nitric oxide synthase (Inos), TNF-α, IL-6, IL-1β, IL-12, and MCP-1." (PMID 28692672, 2017). "To date, a number of studies have shown that myokines, such as interleukin-6 (IL-6), interleukin-15 (IL-15) and brain-derived neurotrophic factor(BDNF), may be potential regulators of many physiological states and metabolic diseases, such as obesity and IR." (PMID 28702069, 2017). "Obesity is often accompanied by low-grade chronic inflammation in adipose tissues, and exhibiting elevated pro-inflammatory cytokines such as tumor necrosis factor-α (TNF-α), interleukin-1β (IL-1β), interleukin-6 (IL-6) and monocyte chemotactic protein-1 (MCP1)." (PMID 26837433, 2016). "IL-6 levels also increase with BMI and obesity in the absence of other disease." (PMID 26743937, 2016). "Thus, the modest obesity-induced pro-inflammatory milieu, involving small increases in systemic IL-6, are unlikely to impact the local IL-6 concentrations and accelerate inflammation-driven cancer progression." (PMID 27351281, 2016). "During the early stages of mild obesity in mice fed a high-fat diet (HFD), obesity not only stimulates infiltration of M1 macrophages, which gives rise to the proinflammatory environment, but also alters secretion of chemokines and cytokines such as TNF-α and IL-6." (PMID 27101398, 2016). "Skeletal muscle activities are inversely related to obesity because obesity accelerates muscle atrophy and decelerates muscle strength via regulating the activities of TNF-α, Ang II, AGEs, Myostatin, exogenous GC, IL-6, I/IGF, vitamin D, Ca2+, estrogen, testosterone and leptin." (PMID 27746742, 2016). "This complex relationship between obesity and BMD could be explained by the effect on bone of a series of adipokines and cytokines secreted by adipose tissue, such as leptin, resistin, adiponectin, interleukin 6, and tumor necrosis factor-alpha." (PMID 27809297, 2016). "Although all these data indicate that resveratrol can alleviate obesity-induced upregulation of IL-6, IL-8, and MCP-1 in adipose tissue, it has not been fully elucidated by which molecular mechanisms resveratrol exerts its effect on IL-6, IL-8, and MCP-1 under inflammatory conditions." (PMID 25926797, 2015). "Interestingly, mice with IL-1β, IL-6, or TNFα receptor knocked out show a worsening rather than a reduction in both obesity and metabolic syndrome, suggesting that inflammation is not the only contributing factor to these afflictions." (PMID 26217222, 2015). "Furthermore, few reports have shown Il6 increase in VAT of obese mice, but to date there has been no report about obesity impact on Il6 expression in SAT of mice." (PMID 25834641, 2015).
Obesity (continued). "In addition to fat cells, it has been shown that in obesity white adipose tissue is infiltrated by macrophages, which may also be a major source of proinflammatory cytokines, TNF-α, IL-6, MCP-1 and iNOS." (PMID 26247962, 2015). "They become the main source of proinflammatory cytokines such as tumor necrosis factor-α (TNF-α) and interleukin (IL)-6, and the chemokine monocyte chemoattractant protein-1 (MCP-1) that is elevated in both the adipose tissue and plasma of mice with diet-induced obesity." (PMID 26516917, 2015). "In addition to IL-6, recent studies suggest that CCL5 is another key player in obesity-related adipose tissue inflammation; gene expression of CCL5 in adipose tissue is increased in obese subjects, and CCL5 increases monocyte migration and macrophage survival in human adipose tissue." (PMID 24918199, 2014). "The inflammatory milieu of obesity is complex, featuring a panoply of elevated plasma and tissue specific cytokines that are increased in some rheumatic diseases and are able to increase the expression of inflammatory cytokines, such as TNF and IL-6, also in the early phases of the disease." (PMID 25426122, 2014). "IL-6 signaling pathways are involved in the liver synthesis of C-reactive protein (CRP), and CRP is elevated in children with sleep-disordered breathing, whereby both IL-6 and CRP levels correlate with degree of hypoxemia and sleep disruption, independently of the degree of obesity." (PMID 24991089, 2014). "On the other hand, there is increased prevalence of obesity among patients with OSAS, and previous evidence suggests that adipose tissue can produce proinflammatory factors, such as C-reactive protein (CRP), tumor necrosis factor-α (TNF-α), interleukin-6 (IL-6), and interleukin-8." (PMID 25538852, 2014). "Together, the altered hormonal and inflammatory milieu of obesity may contribute significantly to cancer growth and progression via promoting mitogenesis (e.g., leptin, IGF-1, insulin), angiogenesis (e.g., VEGF, IL6, IL8), and invasion (e.g., leptin, IL6, PAI-1, CCL5, CCL2)." (PMID 23573093, 2013). "Additionally, controversial studies suggested an increase or no change in serum IL-6 levels in obesity and metabolic syndrome." (PMID 24068858, 2013). "It is well recognized that in obesity, the adipose tissue secretes a distinct quantity of inflammatory cytokines, and some of these, such as tumor necrosis factor-a, (TNF-a) interleukin-1 (IL-1) and interleukin-6 (IL-6), escape into the general circulation provoking systemic symptoms." (PMID 23149391, 2013). "While several studies indicate that increased IL-6 levels correlate with adiposity and fat mass, and not necessarily with insulin action or responsiveness, another study has pointed to higher IL-6 levels in patients with obesity-related insulin resistance." (PMID 24455420, 2013). "In addition, several proinflammatory cytokines and chemokines such as IL-6, TNF-α and MCP-1 are secreted by adipocytes (as well as nonadipocyte cells such as macrophages), thus contributing to the chronic inflammatory state often observed in obesity." (PMID 23690838, 2013). "Mice with diet-induced obesity exposed to oral infection or systemic inoculation of live Porphyromonas gingivalis (P. gingivalis) developed a blunted inflammatory response with reduced expression of TNF, IL-6, and serum amyloid protein A (SAA) when compared with lean mice." (PMID 23922979, 2013). "Furthermore, an increase in ambulatory activity (typically quantified as walking), is known to have a strong inverse correlation with sedentary behaviour, and has been shown to be associated with reduced IL-6 in those with IGT, independent of obesity." (PMID 24205208, 2013). "This could indicate that IL-6 mRNA is not increased by obesity, or that circulating white blood cells in general, and more specifically, white blood cell IL-6 mRNA, are not indicators of adipose tissue inflammation." (PMID 26486919, 2012).
Obesity (continued). "We speculate that Ob myocytes have developed an increased negative control system of IL-6 signaling as a protection against the elevated levels of circulating IL-6 occurring in obesity." (PMID 22761857, 2012). "Obesity can induce increased c-Jun N-terminal kinase (JNK) activity which is activated in response to inflammatory cytokines, free fatty acids, activated NF-κB, and inflammatory mediators, including TNF-α and IL-6, and may contribute to insulin resistance." (PMID 23213270, 2012). "In humans, evidence exists for the ability of insulin to promote inflammation during acute, experimentally-induced hyperinsulinemia, independent of obesity, increasing inflammatory cytokine concentrations in subcutaneous adipose tissue interstitial fluid as well as circulating IL-6 concentrations." (PMID 26486919, 2012). "In agreement with the established evidence, we found increased levels of IL-6 and protein C reactive (CRP) in blood from the morbidly obese group compared with the undetectable amounts of these proinflammatory markers observed in healthy lean controls (p<0.01), a feature that characterizes obesity." (PMID 23110196, 2012). "Other effects of exercise that may affect obesity beyond energy expenditure include: 1) increased brain BDNF levels, 2) decreasing plasma and pancreatic β-cell content of IL-6 and TNF-α, 3) increasing parasympathetic tone, and 4) anti-inflammatory effects of exercise." (PMID 22808000, 2012). "Adipose tissue has garnered a great deal of attention as a potential source of elevated circulating inflammatory cytokines in obesity and insulin resistance due to many studies demonstrating that adipose tissue can synthesize and secrete pro-inflammatory cytokines, including TNF-α and IL-6." (PMID 21054880, 2010). "Obesity, particularly visceral adiposity, is accompanied by chronic low-grade inflammation, indicated by increased serum levels of inflammatory markers such as C-reactive protein (CRP), tumor necrosis factor-α (TNF-α), and interleukin-6 (IL-6) of obese patients." (PMID 22375203, 2010). "Of note, in patients with COPD, increases in IL-6 and TNF-α in the systemic circulation have been linked to obesity and insulin resistance; nevertheless, no reports analyzed the role of inflammation within the adipose tissue itself in metabolic derangements in such patients." (PMID 21197447, 2010). "While the hepatic upregulation of these actors could be important in the progression of liver complications, the real contribution of these proteins for inflammatory cells recruitment into the liver has to be determined, since systemic levels of IL6, TNFα, IP10 and MCP1 are dependent on obesity." (PMID 21042596, 2010). "Because age influences several salivary biomarkers, particularly cortisol and IL-6, the observed group differences may be partially attributable to age rather than obesity alone highlighting the importance of larger studies with more diverse and closely matched cohorts." (PMID 41584074, 2025). "Obesity and metabolic syndrome frequently trigger a systemic inflammatory response; consistently, the analysis of circulating pro-inflammatory cytokines (TNF-α, IL-6, IL-17) demonstrated that HFD exposure increased TNF-α levels and that such an increase could be counteracted by JQ1." (PMID 38365172, 2025). "In addition, many studies have shown that pro-inflammatory cytokines, such as tumor necrosis factor (TNF), interleukin 6 (IL-6), IL-1β, and interferon-gamma (IFN-γ), can influence insulin resistance, adipose tissue inflammation and regulate obesity-related metabolism." (PMID 40931194, 2025). "For example, basal hypothalamic IL-6 level and microglia function maintain hypothalamus homeostasis, which is critical to GLP-1/GLP-1R-mediated food intake control, and its disturbance may impact systemic infections, such as bacterial sepsis and other inflammatory conditions as seen in obesity." (PMID 40592472, 2025).